ASNS (asparagine synthetase (glutamine-hydrolyzing))
Synonyms: TS11; ASNSD
Tractability: Small molecule: a structure with a bound ligand is known; a high-quality ligand is known. PROTAC: ubiquitination databases record sites on it; its protein half-life has been measured; a small molecule that binds it is known.
Target class: Enzyme
Gene: Protein-coding gene on chromosome 7 (97,851,677 to 97,872,542, reverse strand). Ensembl gene ENSG00000070669.
Subcellular location (Human Protein Atlas): Cytosol
Pathways (Reactome):
Cellular responses to stimuli: ATF4 activates genes in response to endoplasmic reticulum stress; Response of EIF2AK1 (HRI) to heme deficiency; Response of EIF2AK4 (GCN2) to amino acid deficiency
Metabolism: Aspartate and asparagine metabolism
Gene Ontology:
Molecular function: asparagine synthase (glutamine-hydrolyzing) activity; protein binding; glutaminase activity
Biological process: cellular response to glucose starvation; L-asparagine biosynthetic process; negative regulation of apoptotic process; positive regulation of mitotic cell cycle
Cellular component: cytosol
Genetic constraint (gnomAD): Loss-of-function variants: 33 observed, 59.26 expected, observed/expected ratio (o/e) 0.56, 90% interval 0.42 to 0.75. The upper end of that interval is the gene's LOEUF score, 0.75, which puts it in group 3 of 6, group 1 being the genes least tolerant of losing a copy. Missense variants: 495 observed, 664.86 expected, observed/expected ratio (o/e) 0.74, 90% interval 0.69 to 0.8. Synonymous variants: 197 observed, 235.82 expected, observed/expected ratio (o/e) 0.84, 90% interval 0.74 to 0.94.
Gene-disease validity (ClinGen):
ClinGen rates the evidence that ASNS causes each of these diseases.
congenital microcephaly - severe encephalopathy - progressive cerebral atrophy syndrome (autosomal recessive): Definitive.
Homologues: Orthologues: chimpanzee ASNS (99% identical), macaque ASNS (98% identical), dog ASNS (95% identical), mouse Asns (94% identical), rat Asns (94% identical), pig ASNS (90% identical), rabbit ASNS (86% identical), tropical clawed frog asns (78% identical), zebrafish asns (71% identical). Paralogues in human: ASNSD1 (19% identical).
Diseases named in the same sentence as ASNS in open-access papers:
ASNS is named in the same sentence as 87 diseases in open-access papers, as found by Europe PMC text mining. Sharing a sentence is not in itself a finding about the gene and the disease. The quoted sentences say what the papers report.
breast carcinoma (25 papers, 2018 to 2025). "ASNS has been implicated in breast cancer tumorigenesis, as its reduced expression inhibits proliferation and induces cell cycle arrest." (PMID 40362379, 2025). "ASNS upregulation caused by arginine depletion leads to cell death in MDA-MB-231 breast cancer cells by exhausting intracellular aspartate and disrupting the malate-aspartate shuttle needed for mitochondrial function." (PMID 40813699, 2025). "In our study, the low expression of ASNS in HER2-positive breast cancer is associated with patient survival, which may be due to ASNS-mediated asparagine synthesis in tumor cells." (PMID 35663326, 2022). "In contrast, ASNS expression was significantly up-regulated in breast cancer, with the highest expression in Basal-like subtypes." (PMID 40781327, 2025). "In melanoma and breast cancer cells, downregulation of ASNS induced cell cycle arrest, which significantly inhibited the growth of cancer cells." (PMID 38206293, 2024). "Previous studies have demonstrated that ASNS is overexpressed in various cancers, including gastric, lung, and breast cancers." (PMID 38474084, 2024). "In breast cancer, downregulation of the ASNS protein also induced cell cycle arrest and inhibited cell growth." (PMID 39210809, 2024). "ASNS inhibition can suppress breast cancer metastasis, as the ASNS enzyme produces Asn, which is directly involved in activation of various transcriptional factor such as SNAIL, TWIST WLAN." (PMID 39093903, 2024). "ASNS catalyzes the synthesis of asparagine from aspartate and glutamine, is overexpressed in several cancers including gastric cancer, liver cancer, breast cancer, and colorectal cancer and promotes cell proliferation, chemoresistance, and metastasis." (PMID 37387559, 2023). "The expression of glutamine synthetase (GS) and asparagine synthetase (ASNS) is correlated with poor prognosis in breast cancers." (PMID 37046596, 2023). "It was suggested that at least in breast cancer cells, such depletions are in part due to the ER-stress mediated activation of ASNS (asparagine synthetase), which depletes aspartate and diminishes aspartate-malate shuttle, negatively impacting TCA." (PMID 34298755, 2021). "Downregulation of ASNS induces cell cycle arrest in breast cancer cells and inhibits the proliferation." (PMID 34540668, 2021). "In human melanoma and breast cancer, knockdown of ASNS has been demonstrated to suppress cell growth via inducing cell cycle arrest." (PMID 34540668, 2021). "This is consistent with our results, where MDA-MB-231 cells cultured with EqMDEC CM underwent cell death through apoptosis and showed downregulation of CX3CL1, ASNS, and LCN2, three genes associated with breast cancer progression." (PMID 33239740, 2020). "In breast cancer cells, ASNS is a target of IGF1/IGF2-dependent anabolic signaling, and, consistently, ASNS silencing depressed cell proliferation in two distinct cell lines, one of which derives from a triple negative tumor." (PMID 31998641, 2019). "Expression of human asparagine synthetase (ASNS) promotes metastatic progression and tumor cell invasiveness in colorectal and breast cancer, presumably by altering cellular levels of L-asparagine." (PMID 31552298, 2019). "Importantly, in HER2-positive breast cancer, decreased expression of metabolism-related genes ATIC, HPRT1, ASNS, SULT1A2, and HAL was associated with increased survival." (PMID 35663326, 2022). "This may be because down-regulating ASNS expression can reduce the accumulation of pyrimidine bases in breast cancer cells, which is consistent with our findings that ASNS expression is elevated in triple-negative breast cancer." (PMID 35663326, 2022). "Indeed, ASNS knockdown and dietary reduction of asparagine suppress breast cancer progression, indicating that ASNS can be a therapeutic target to inhibit metastasis formation in patients." (PMID 33401771, 2021).
breast carcinoma (continued). "The other one is expression of asparagine synthetase (AsnS), involved in the synthesis of the conditionally essential amino acid asparagine, which allows for breast cancer cell invasiveness and metastasis as there is a disproportionately high asparagine content of cEMT-associated proteins." (PMID 33022920, 2020). "Moreover, ASNS expression and Asn availability have been found to be strongly correlated with the metastatic behavior of breast cancer." (PMID 31998641, 2019). "For breast cancer cases, similar to gastric cancer, characteristic proteins are ASNS and Cyclin_B1, whereas for cases similar to thyroid carcinoma, characteristic proteins with increased expression are Caveolin-1, Collagen_VI, PR, MAPK_pT202_Y204, and ER-alpha." (PMID 30442178, 2018). "Furthermore, asparagine levels or ASNS (asparagine synthetase) activity could also determine the metastatic capacity of breast cancers both in vivo and in vitro." (PMID 33292758, 2020). "Indeed, knockdown of ASNS, in combination with l‐asparaginase treatment or dietary restriction of asparagine, suppressed breast cancer progression, implying that asparagine metabolism could be a promising therapeutic target to prevent metastasis formation in breast cancer." (PMID 40552664, 2025). "Conversely, in both breast cancer cell lines, O-desmethyltramadol consistently downregulated the expression of SLC16A1, CD22, NUPR1, ASNS, and DDIT3." (PMID 40362379, 2025). "Compared with normal control tissues, the expression of HPRT1, ASNS, ATIC, SULT1A2, and HAL was significantly increased in HER2-positive breast cancer samples." (PMID 35663326, 2022). "Experimental studies have shown that CDKN2A, PSAT1, HMGB1, ELAVL1, and SLC7A11 were up-regulated in TNBC, ASNS and LAMP2 were up-regulated in breast cancer and CAV1 was down-regulated in breast cancer, and HELLS was up-regulated in other tumors." (PMID 36568247, 2022). "In several human tumors, such as diffuse large B-cell lymphoma, colorectal cancer, breast cancer and sarcoma, 4E-BP1 levels were positively correlated with ATF4-target genes, including ASNS." (PMID 31998641, 2019). "Therefore, aspartate insufficiency, resulting from arginine starvation-induced ASNS upregulation, can be considered an important vulnerability in arginine-starved ASS1-low breast cancer cells." (PMID 31052256, 2019). "In addition, ATIC, HPRT1, ASNS, SULT1A2, and HAL may represent attractive therapeutic targets for HER2-positive breast cancer, and require further validation studies, especially considering that treatment with specific inhibitors may alter the expression of these metabolic genes." (PMID 35663326, 2022). "In addition, the possible ferroptosis mechanisms of CDKN2A, PSAT1, SLC7A11, LAMP2, CAV1, and HMGB1 in TNBC and ASNS, ZFP69B, ELAVL1, TF, HELLS, and DPP4 in breast cancer have not been reported." (PMID 36568247, 2022).
leukemia (16 papers, 2014 to 2024). A malignant (clonal) hematologic disorder, involving hematopoietic stem cells and characterized by the presence of primitive or atypical myeloid or lymphoid cells in the bone marrow and the blood. "The expression of ASNS is ultimately associated with the resistance of leukaemia cells and leukaemic lymphoblasts to asparagine depletion." (PMID 32273511, 2020). "In ALL, numerous studies have reported that ASNS expression is elevated in asparaginase-resistant leukemia cells compared to asparaginase-sensitive cells, and ASNS expression levels have been correlated with asparaginase sensitivity in PDAC cell lines." (PMID 38951899, 2024). "Analysis of our results in the context of GCN2 and ASNS mRNA expression levels from normal samples and from different leukemia types suggests interesting relationships." (PMID 30364637, 2018). "The importance of asparagine for tumor growth has been demonstrated in leukemia cells expressing a low level of asparagine synthetase (ASNS)." (PMID 28811348, 2017). "Thus, ASNS expression is a predictive biomarker in several human cancer types whereas asparaginases, that degrade extracellular asparagine, are a key chemotherapeutic drug for the treatment of leukemia and lymphomas that lack ASNS expression." (PMID 33822775, 2021). "However, more recent results from the same group, obtained with a murine leukemia model of ASNS-null ALL, indicate that, actually, glutaminase activity was needed for a durable suppression of the tumor." (PMID 31998641, 2019). "L-asparaginase associated with high ASNS expression may be overcome by the use of ASNS inhibitor as reported in an in vitro study of L-asparaginase resistance leukemia cell line." (PMID 28750681, 2017). "Early studies have shown that upregulated expression of ASNS could be related to the resistance of leukemia cells to L-aspartase, which is widely used as an active component in the treatment of pediatric acute lymphocytic leukaemia and some types of acute myeloid leukaemia." (PMID 36457747, 2022). "Thus, we hypothesize that leukemias exhibiting high GCN2 expression and low ASNS expression may be susceptible to pharmacologic GCN2 inhibition." (PMID 30364637, 2018). "For instance, asparagine synthetase (ASNS), an enzyme that catalyzes the conversion of aspartate and glutamine to asparagine and glutamate in an ATP-dependent manner, has been shown to increase the chemotherapy sensitivity of leukemia cells resistant to L-asparaginase when inhibited." (PMID 27296290, 2016). "Amino sulfoximines directly inhibit ASNS activity, whereas asparaginase, an FDA-approved drug widely used in the treatment of leukemia, hydrolyzes asparagine to aspartate and ammonia." (PMID 26499495, 2015). "Expression of asparagine synthetase (ASNS), which catalyzes the synthesis of asparagine, is negatively correlated with L-ASP’s anticancer activity in leukemia cell lines, leukemia patient samples, and ovarian cancer cell lines." (PMID 25177232, 2014). "It had been known that leukemia and lymphoma require asparagine for growth in cell culture due to absence of ASNS expression." (PMID 28750681, 2017). "ASNase has been a cornerstone of the treatment of leukaemia for decades, but given the results of our work, ASNS may also be a novel therapeutic target in non-malignant, autoimmune disease mediated by the GC reaction, and is deserving of future study in this context." (PMID 39671468, 2024).
acute lymphoblastic leukemia (15 papers, 2016 to 2025). Leukemia with an acute onset, characterized by the presence of lymphoblasts in the bone marrow and the peripheral blood. "Asparagine synthetase (ASNS) is associated with asparaginase therapy in acute lymphoblastic leukemia." (PMID 35625787, 2022). "Clinically, ASNS dysfunction is associated with childhood acute lymphoblastic leukemia (ALL) and asparagine synthetase deficiency (ASD)." (PMID 37528150, 2023). "Furthermore, A6E mutation could be introduced to the ASNS gene of acute lymphoblastic leukemia patients to inhibit the upregulation of ASNS by cancer cells, reducing the risk of developing resistance to the asparaginase treatment." (PMID 33916846, 2021). "For instance, the gene encoding for the asparagine synthetase (ASNS) enzyme is commonly silenced in acute lymphoblastic leukemia (ALL), rendering ALL cells auxotrophic for asparagine." (PMID 34256164, 2021). "High levels of asparagine synthetase (ASNS) in acute lymphoblastic leukemia (ALL) lead to immunotherapy resistance." (PMID 40808257, 2025). "ASNS dysfunction has been clinically associated with ASNS deficiency (ASD) and childhood acute lymphoblastic leukemia." (PMID 39093903, 2024). "In addition, the A6E mutation codon could be incorporated into the ASNS gene of patients with acute lymphoblastic leukemia to minimize the risk of developing a resistance to the asparaginase treatment, as A6E mutation can block the attempt at ASNS overexpression by the cancer cells." (PMID 33916846, 2021). "ASNS has received considerable attention in childhood acute lymphoblastic leukemia (ALL), since increased ASNS activity in human leukemic cells is one of the causes of their resistance to L-asparaginase." (PMID 31681605, 2019). "Acute lymphoblastic leukemia cells are sensitive to L-asparaginase treatment because of their poor ability to synthesize sufficient amounts of endogenous L-Asn due to low expression levels of L-asparagine synthetase (ASNS)." (PMID 38792133, 2024). "Studies have revealed that ASNS expression is higher in some solid tumors compared to acute lymphoblastic leukemia (ALL) and this enzyme confers the tumor cells with increased adaptability to asparagine depletiona." (PMID 41316157, 2025). "The aspartate synthetase ASNS is a focus of clinical attention, because the imbalance of the expression of ASNS in children’s acute lymphoblastic leukemia (ALL) cells is considered to offset the impact of a first-line therapy for ALL that depletes asparagine." (PMID 36998464, 2023). "In acute lymphoblastic leukemia (ALL), primary cells and many ALL cell lines exhibit a low expression level of ASNS." (PMID 36793607, 2023). "For instance, in acute lymphoblastic leukemia (ALL), in which low ASNS expression was found, further depletion of asparagine achieved by the introduction of asparaginase (hydrolyzing asparagine to aspartic acid and ammonia) was shown to be lethal in ALL cells and used as a treatment strategy." (PMID 35158820, 2022). "For example, primary Acute Lymphoblastic Leukemia (ALL) cells and many ALL cell lines exhibit a particularly low level of ASNS expression and thus are unusually sensitive to asparagine depletion." (PMID 29299118, 2017).
prostate carcinoma (9 papers, 2019 to 2025). A carcinoma that arises from epithelial cells of the prostate gland. "Overexpression of ASNS mRNA was detected in integrated analysis of surgically resected specimens from castration-resistant prostate cancer and was associated with ASNS protein levels." (PMID 39796613, 2025). "Increased ASNS expression is linked to unfavorable outcome in multiple solid malignancies, including prostate cancer, HCC, and glioma." (PMID 40416363, 2025). "OGDHL and ASNS alterations and their association with prostate cancer patient survival (a proxy of tumour aggression) were investigated in cBioPortal." (PMID 37196186, 2023). "Accumulating evidence establishes asparagine synthetase (ASNS) as a critical driver of malignant progression in solid tumors including prostate cancer, where it sustains tumorigenesis through dual metabolic reprogramming." (PMID 41179661, 2025). "More recently, ASNS mRNA overexpression, due to increased copy number of the gene, was detected in surgical specimens of castration-resistant prostate cancer and correlated with ASNS protein abundance." (PMID 31998641, 2019). "Given that recent studies have shown glutamine metabolism upregulates ARPC1A in prostate cancer and ASNS is a key enzyme in glutamine metabolism, it may mediate ARPC1A upregulation." (PMID 39867911, 2024). "We validated the expression levels of 5 prognostic genes in the TCGA-PRAD and found that both ATCAY and GLUL were lower expressed in the tumor tissues than normal prostate tissues, while the ASNS, CAD and FPGS were overexpressed in the prostate cancer group." (PMID 36983244, 2023).
lung carcinoma (8 papers, 2020 to 2025). "Here, we reported that high ASNS expression was one of the characteristics of lung cancer cells in LN metastasis, which played an essential role in the interaction between immunocytes and tumor cells within metastatic TdLNs." (PMID 41208878, 2025). "In this study, we have identified that lung cancer cells with high expression of ASNS have an increased propensity for LN metastasis." (PMID 41208878, 2025). "In lung cancer cells and epidermoid carcinoma cells, ASNS knockdown reduces proliferation by arresting the Go/G1 cell cycle." (PMID 38474084, 2024). "ASNS expression is significantly up-regulated in a variety of human tumors, including liver cancer, lung cancer, and other malignant tumors." (PMID 39445026, 2024). "It suppresses MMP-24 and upregulates activating transcription factor 4 (ATF4) and asparagine synthetase (ASNS), an enzyme controls the motility of lung cancer cells by endowing stability to the β-catenin complex and modifying mitochondrial response." (PMID 37241719, 2023). "A previous study also demonstrated that ASNS was recognized by ATF4 and contributes to protein biosynthesis in lung cancer." (PMID 34976799, 2021). "We next verified that the AHR activator omeprazole induced expression of ASNS and ATF4 in three different lung cancer cell lines, H1975, A549, and H1299." (PMID 33214553, 2020).